ENSG00000284772 (novel transcript)
Gene: Protein-coding gene on chromosome 15 (43,614,208 to 43,632,283, reverse strand). Ensembl gene ENSG00000284772.
Genetic constraint (gnomAD): Missense variants: 32 observed, 30.3 expected, observed/expected ratio (o/e) 1.06, 90% interval 0.8 to 1.42. Synonymous variants: 12 observed, 10.72 expected, observed/expected ratio (o/e) 1.12, 90% interval 0.71 to 1.74.